BDNF (brain derived neurotrophic factor)
Diseases named in the same sentence as BDNF in open-access papers (continued):
Sharing a sentence is not in itself a finding about the gene and the disease.
mental disorder (continued). "The results of this paper show that alterations in BDNF, inflammatory cytokines, and oxidative stress are still rarely studied in BPD, indicating that the search for specific biomarkers and molecular pathways for this mental disorder are still in the very beginning." (PMID 36946840, 2023). "Brain-derived neurotrophic factor (BDNF) is another important protein for brain development and its low presence may be responsible for the observed reduced plasticity in patients with severe mental disorders." (PMID 33762975, 2021). "We cannot conclude whether these changes in BDNF and IGF-1 concentrations are exclusive to cocaine addiction or not because new studies in psychiatric patients with no history of drug use will be necessary to elucidate their role in mental disorders." (PMID 25734326, 2015). "Notably, BDNF and oxidative stress markers are not merely independent indicators of neurodegeneration, as recent studies have shown an inverse relationship between them in various neurodegenerative and mental disorders." (PMID 40361833, 2025). "The difference in both ACTH and BDNF levels found in our study between patients with and without NSSI seems to be important and may be the basis for further research on the mechanisms underlying comorbidity of mental disorders and NSSI." (PMID 38137402, 2023). "The effect of BDNF rs10835210 and DRD4 rs1800955 on mental disorder development was not investigated in the ethnic Russian population." (PMID 38397229, 2024).
glaucoma (122 papers, 2006 to 2026). Increased pressure in the eyeball due to obstruction of the outflow of aqueous humor. "There are several studies using different models of glaucoma that indicate that local administration of BDNF to the eye results in reduced loss of RGCs." (PMID 38562304, 2024). "In this review, we discuss the known mechanisms of retinal cell injury in glaucoma with a particular focus on an important molecular mechanism underlying BDNF/TrkB signaling mediated by Cav-1 and Shp2 phosphatase and its implications in glaucoma pathogenesis." (PMID 37962455, 2024). "Nonetheless, further studies are needed to clarify the causal link between BDNF and glaucoma and to assess the effectiveness of BDNF supplementation as a neuroprotective treatment." (PMID 39458902, 2024). "The effects of the BDNF Met allele on various neurological and neurodegenerative disorders including Parkinson’s disease, AD, multiple sclerosis, glaucoma and neuromyelitis optica have been reported and reviewed previously." (PMID 38916728, 2024). "This was supported by the finding that the therapies that significantly preserved the RGCs in the rat model of glaucoma were associated with elevated BDNF expression as compared to the untreated controls." (PMID 35668928, 2022). "In experimental models of glaucoma, overexpression of BDNF alleviated RGC loss after optic nerve injury and improved RGC survival, but this effect is time-limited because of downregulation of TrkB (the BDNF receptor)." (PMID 36414808, 2022). "In vivo models of AD, acute optic nerve injury, and experimental glaucoma demonstrated the neuroprotective effects of virally administered BDNF by attenuating behavioral deficits, preventing neuron loss, and increasing RGC survival, respectively." (PMID 36361771, 2022). "In models of glaucoma, BDNF therapy can delay or halt RGCs loss, but this protection is time-limited." (PMID 32872441, 2020). "On the other hand, genome-wide association studies show a correlation between mutations in some NTF genes—NT-4 and BDNF—and the occurrence of glaucoma." (PMID 31484425, 2019). "BDNF gene therapy can improve RGC survival in experimental models of glaucoma, the leading cause of irreversible blindness worldwide." (PMID 30258047, 2018). "While these results offer promise for the use of neuroprotective strategies in glaucoma, overexpression of BDNF can cause tachyphylaxis of the survival response through downregulation of TrkB and its subsequent degradation." (PMID 29853847, 2018). "Interruption of retrograde axonal transport of target-derived BDNF and its receptor TrkB has been shown to contribute to the loss of RGCs in glaucoma." (PMID 22496848, 2012). "Adeno-associated virus (AAV) vectors are currently the predominant choice for glaucoma gene therapy delivery, encoding genes such as BDNF, EPO, and NRF2, enabling uncontrolled expression of target genes in AAV-transduced cells in both in vivo and in vitro models." (PMID 39744428, 2025). "Further, the BDNF Val66Met polymorphism is significantly correlated with variations in retinal thickness, indicative of its role in the pathophysiology of ocular diseases such as glaucoma and neuromyelitis optica spectrum disorders." (PMID 38916728, 2024). "Nevertheless, more efforts are required to reach conclusions about the causal relationship between BDNF and glaucoma as well as whether the supplementation of BDNF is effective as a neuroprotective therapy for glaucoma." (PMID 36579616, 2022). "Therefore, it is likely that aberrant BDNF expression and the underlying signaling pathways in the visual system paly a key role in the pathophysiology of glaucoma." (PMID 35668928, 2022). "For example, an investigation into the relationship between the systemic levels of BDNF and the risk for the development and/or the rate of glaucoma progression may prove beneficial in predicting its possible utility as a biomarker." (PMID 35668928, 2022).
glaucoma (continued). "It has been suggested that the blockade of axonal transport that leads to deficits in BDNF at the cell body may cause RGC death in glaucoma." (PMID 27657046, 2016). "Numerous studies have indicated that the cell death of RGCs in glaucoma may be associated with a deficit of neurotrophins, including BDNF." (PMID 25893192, 2015). "Decreases in BDNF signaling are also associated with glaucoma and retinal degeneration." (PMID 25426041, 2014). "Thus, the mechanism of glaucoma development according to the BDNF (rs2030324) polymorphism remains unclear." (PMID 25893192, 2015). "In glaucoma, this transport is blocked at the optic nerve head, depriving RGCs of brain-derived neurotrophic factor (BDNF) support from the lateral geniculate nucleus (LGN), leading to RGCs apoptosis in glaucoma." (PMID 41576145, 2026). "Activation of pro-survival cell-signalling pathways by modulation of brain-derived neurotrophic factor (BDNF) signalling has been suggested as a possible treatment for glaucoma." (PMID 39516652, 2025). "Upregulation of BDNF is observed in both experimental glaucoma cases and optic nerve axotomy experiments, and BDNF has proven neuroprotective effects through promoting the survival and development of RGCs in vitro in several studies." (PMID 40371387, 2025). "Several biosensors have been developed for BDNF detection, including: 3D aptasensors based on biolayer interferometry technology for early detection of glaucoma and BDNF and MIP‐based synthetic receptors." (PMID 39688117, 2025). "Previous experimental studies have demonstrated the involvement of BDNF in the mechanisms of glaucoma, diabetic retinopathy and age-related macular degeneration." (PMID 40513379, 2025). "In this study, we describe the advancement of a gene therapy that combines TrkB and BDNF to offer a synergistic approach to glaucoma treatment by simultaneously addressing the limitations of BDNF monotherapy and enhancing TrkB receptor activity." (PMID 40838110, 2025). "As previously elucidated, the neuroprotective effects of brain-derived neurotrophic factor (BDNF) in a rat model of glaucoma are mediated through the enhancement of both anterograde and retrograde axonal transport via intravitreal administration of BDNF." (PMID 39744428, 2025). "The modified peptide studied herein showed improved stability over the original peptide (RNYK) and demonstrated potential for use as a BDNF agonist with neuroprotective properties for treatment of neurodegenerative disorders such as glaucoma." (PMID 38638624, 2024). "In glaucoma, preclinical studies targeting neuroprotection have attempted to overcome limitations regarding long-term expression of the neurotrophic factor BDNF and safety issues from off-target effects of antiapoptotic proteins." (PMID 38618935, 2024). "It has been shown that BDNF protects RGCs’ survival in pathological conditions such as glaucoma and optic nerve injury." (PMID 38585147, 2024). "Given the potential role of BDNF signalling in glaucoma development, its application as a neuroprotective agent has been explored." (PMID 39423611, 2024). "Disruptions in the retrograde transport and reduced levels of BDNF in the serum and ocular fluids of patients with glaucoma suggest that neurotrophic deprivation contributes to glaucomatous optic neuropathy." (PMID 38818519, 2024). "In a mouse model of glaucoma, administration of BDNF resulted in increased survival of the RGC and improved retinal function." (PMID 38585147, 2024). "Collectively, these findings posit that Müller cell-derived neurotrophic factors, with particular emphasis on BDNF, hold paramount importance in protecting RGCs against glaucoma." (PMID 38983026, 2023). "Among the neurotrophic factors, BDNF and its receptor TrkB are postulated to be pivotal in upholding the integrity of RGCs in glaucoma." (PMID 38983026, 2023).
glaucoma (continued). "For example, intravitreal administration AAV vectors expressing the brain-derived neurotrophic factor (BDNF) showed protection of retinal ganglion cells, and reduced the intraocular pressure in a rat glaucoma model." (PMID 36992407, 2023). "This aspect is noteworthy, since BDNF was reported to be involved in the pathogenesis of some major neurodegenerative diseases of the eye, such as glaucoma." (PMID 35889920, 2022). "Further we discuss the challenges and future strategies to explore the utility of BDNF in the management of glaucoma." (PMID 35668928, 2022). "Combined overexpression of BDNF and TrKB was effective in stimulating axon transport in an experimental glaucoma model." (PMID 36414808, 2022). "In contrast to NGF, investigations into effects of brain-derived neurotrophic factor, neurotrophin-4 (bind TrkB), and neurotrophin-3 (bind to TrkC) on the ocular surface are sparse, certainly less than those on the retina and on glaucoma." (PMID 36430547, 2022). "In this review, the authors discuss the neuroprotective role of BDNF in promoting the survival of RGCs and its possible application as a therapeutic tool to meet the challenges in glaucoma management." (PMID 35668928, 2022). "Compared to the control group, BDNF levels in the blood of primary open-angle glaucoma patients and in the tears of normal-tension glaucoma patients were significantly lower." (PMID 35668928, 2022). "BDNF levels are notably low in glaucoma patients, and treatment with BDNF can be protective in glaucoma models." (PMID 38983517, 2022). "The authors highlight the exogenous application of BDNF in the experimental model of glaucoma and its limitations when translating research findings into clinical application." (PMID 35668928, 2022). "We also highlight the possibility of using BDNF as a biomarker in neurodegenerative disease such as glaucoma." (PMID 35668928, 2022). "Moreover, exogenous NTF including BDNF administration was shown reduce neuronal loss in animal models of various neurodegenerative diseases, indicating the possibility that exogenous BDNF may be a treatment option in glaucoma." (PMID 35668928, 2022). "While the effects of BDNF in the protection of retinal ganglion cells are evident, the therapeutic use of BDNF in chronic models of glaucoma is still at the stage of preliminary experiments." (PMID 35269763, 2022). "In this review, the authors discuss the role of BDNF as a potential biomarker for the early detection of glaucoma." (PMID 35668928, 2022). "The expression of BDNF and TrkB were decreased in the optic nerve and retina in glaucomatous marmosets, in accordance with the data assembled from observations of glaucoma patients." (PMID 34561506, 2021). "In glaucoma, BDNF has already been shown to modulate neuroprotection, highlighting the potential of HMGB1 as a target for possible intervention in glaucoma." (PMID 34943212, 2021). "Researchers further constructed MSCs that stably overexpress BDNF and used these cells for intraocular transplantation experiments in glaucoma animal models." (PMID 34356611, 2021). "Supporting this, past studies reported the neuroprotective effect of BDNF on retinal cells in animal glaucoma models and hypoxia- and glucose deprivation-induced injury models." (PMID 34045544, 2021). "Six weeks after the induction of unilateral glaucoma, there was a bilateral decrease of BDNF concentration in the retina, in five of the six rats." (PMID 32872441, 2020). "For instance, in a mouse model of spontaneous glaucoma, eye drops based on brain derived neurotrophic factor prevent the reduction in RGC number thus increasing PERG responses." (PMID 33291737, 2020). "Answering the question concerning the dependence of TrkB expression on BDNF changes in the glaucoma pathology and after treatment is crucial for designing efficient clinical trials." (PMID 32872441, 2020).
glaucoma (continued). "We decided to inject AAV-BDNF three weeks prior to glaucoma induction to ensure stable BDNF overexpression in the retina prior to glaucomatous changes development." (PMID 32872441, 2020). "Attention should be paid to the intriguing result of a bilateral decrease in BDNF concentration in retinas after unilateral glaucoma induction, and of the bilateral increase in BDNF after unilateral transgene administration." (PMID 32872441, 2020). "We showed that the IOP elevation in both Glaucoma and BDNF transgene-expressing groups followed a similar pattern, in line with observations made in mice subjected to optic nerve crush or laser-induced OHT." (PMID 32872441, 2020). "We conclude that for glaucoma therapy, the careful selection of the appropriate BDNF concentration is the main factor securing the long-term responsiveness of RGCs and the maintenance of normal TrkB levels." (PMID 32872441, 2020). "We examined quantitatively the retinal concentrations of the TrkB protein in relation to BDNF, in a course of adeno-associated viral vector gene therapy (AAV2-BDNF), using a microbead trabecular occlusion model of glaucoma." (PMID 32872441, 2020). "We will show that unilateral glaucoma leads to the bilateral reduction in BDNF concentration, accompanied by up to a four-fold TrkB upregulation." (PMID 32872441, 2020). "Again, the importance of BDNF overexpression for the protection of RGCs in the peripheral zone has been confirmed by the significant interaction of glaucoma with BDNF overexpression (p = 0.0003)." (PMID 32872441, 2020). "The present study demonstrated that the application of BDNF increased the expression of synaptic vesicle proteins in the inner retina after the induction of glaucoma." (PMID 31142572, 2019). "These initial findings show the capability of BDNF to induce beneficial synaptic changes in glaucoma." (PMID 31142572, 2019). "Although there are studies showing synaptic rearrangements and dendritic shrinkage after glaucoma induction, BDNF application exhibited a delay in dendritic retraction." (PMID 31142572, 2019). "The present study demonstrated that the levels of synaptic vesicle proteins in RGCs and bipolar cells increased after the application of BDNF in a rat model of glaucoma using chronic elevation in IOP." (PMID 31142572, 2019). "The present study attempted to discover changes in the synapse using brain-derived neurotrophic factor (BDNF) after glaucoma induction by chronic intraocular pressure elevation in a rat model." (PMID 31142572, 2019). "As shown in our western blot analysis, there is an increase in BDNF expression at week 1 after glaucoma induction in the PBS-injection group." (PMID 31142572, 2019). "After the induction of glaucoma, the BDNF-injected group exhibited increases in the total number of ribbon synapses, as seen using electron microscopy." (PMID 31142572, 2019). "Therefore, upregulated BDNF by niacin treatment might decrease the risk of glaucoma." (PMID 29565276, 2018). "Application of extracts from pre-degenerated peripheral nerves stimulate RGC survival through induction of endogenous retinal BDNF expression in glaucoma." (PMID 30524222, 2018). "The axonal transport of BDNF and TrkB receptor are suggested to be obstructed in both acute and chronic experimental glaucoma models, suggesting that deprivation of BDNF to RGCs contributes to the pathogenesis of neuronal loss in glaucoma." (PMID 29896439, 2018). "One such concept is the alteration in the transport of brain-derived neurotrophic factor (BDNF) to RGC somata observed in rodent glaucoma models, along with evidence showing that intravitreal injections of BDNF can lower the rate of RGC loss." (PMID 29914056, 2018). "Neurotrophin deprivation, mainly BDNF, is considered as one of the leading causes of RGC death in glaucoma." (PMID 30524222, 2018).